STAT1 (signal transducer and activator of transcription 1)
Diseases named in the same sentence as STAT1 in open-access papers (continued):
Sharing a sentence is not in itself a finding about the gene and the disease.
tumor (continued). "It was revealed that the binding of GZMA to the LDPRSFLL motif at the N-terminus of F2R promotes apoptosis via JAK2/STAT1 signaling, which in synergy with the PD-1 mAb therapy led to tumor suppression in both mouse model and HCC patients." (PMID 35256589, 2022). "Jak-STAT signaling pathway inhibition is involved in anti-tumor activity in several pre-clinical studies and continued activation of STAT1 and STAT2,which are essential components of JAK/STAT pathway, are associated with suppressing tumor apoptosis." (PMID 35392800, 2022). "We had previously observed that PD-1 was strongly induced in T-lymphocytes of tumour-bearing Stat1−/− mice orthotopically injected with Stat1 competent aggressive HNSCC." (PMID 35595823, 2022). "Recent studies conducted by our group identified the critical anti-tumour role of STAT1 in the host immune response to HNSCC." (PMID 35595823, 2022). "STAT1 has been shown to regulate cell cycle progression by modulating the expression of cyclin D1 in tumour cells." (PMID 35781872, 2022). "Stat1 has been shown to be crucial for the development of Th1-polarized effector function in T lymphocytes and to be tumor-suppressive in mice." (PMID 35618311, 2022). "Together, these results highlight the important role of tumour-derived STAT1 in promoting the accumulation of immunosuppressive myeloid populations, especially when these host derived immune cells are Stat1 deficient." (PMID 35595823, 2022). "HCC tissues with positivity for tumor cell nuclear STAT1 had high cytoplasmic STAT1, suggesting our in vitro data showed that prolonged activation of STAT1 phosphorylation results in increased total STAT1 protein levels." (PMID 35267462, 2022). "In agreement, our results support a tumor-promoting effect of STAT1 expression and activation since it is upregulated at early stages of H. pylori-induced inflammation and increases along the progression of gastric lesions to GC." (PMID 35456965, 2022). "TRIM24 also binds to the RARE of STAT1 promoter to inhibit STAT1 expression and promotes expressions of tumor-suppressive factors such as p21, Bmyc, and hepatocyte nuclear factor 6 (HNF6)." (PMID 36100865, 2022). "The expression of genes as expressed by miR-145-5p is similar to the signal transducer and activator of transcription 1 (STAT1) pathway which is a majorly tumor suppressor." (PMID 35035811, 2022). "We found that it can upregulate cyclin G2 protein expression in macrophages, and cyclin G2 activates the IFN-γ-STAT1 signaling pathway, thereby affecting the tumor microenvironment." (PMID 36566226, 2022). "As mechanism of action, miR130b downregulated tumor OX40L expression by directly targeting IFNAR1/p-STAT1 axis, recruiting Th17 cells via OX40/OX40L interaction, thereby promoting immunosuppressive function of Th17 cells." (PMID 35301282, 2022). "STAT1β lacks most of the transactivation domain of STAT1 and mice expressing STAT1β exhibit defects in IFNγ signaling and decreased NK cell-dependent anti-tumor activity." (PMID 35269659, 2022). "Upregulation of STAT1 and STAT1‐driven genes was also observed in bone metastatic subline with invasiveness derived from ARCaP‐Fast tumour." (PMID 35908276, 2022). "Specifically, while there is some evidence that STAT1 can induce tumorigenesis, accumulating evidence has shown that STAT1 is a tumor suppressor, exerting its anti-tumor role by interfering with the tumor microenvironment and/or signaling pathway." (PMID 35692770, 2022). "Studies in which myeloid STAT3 is ablated show that the myeloid compartment shifts from STAT3- to STAT1-driven signaling, thereby skewing to an anti-tumor response." (PMID 35406557, 2022). "In NPM1–TYK2 tumor tissue, high fusion kinase activity resulted in the upregulation of phosphorylated STAT1, STAT3, and STAT5." (PMID 35042970, 2022). "As a member of the STAT family, STAT1, as a tumor inhibitor, is closely related to cell growth inhibition which can inhibit proliferation and promote apoptosis of the tumor." (PMID 35321506, 2022).
tumor (continued). "CD274 (PD-L1) and PDCD1LG2 (PD-L2) are involved in immunosuppression by tumor cells to evade cytotoxic T cell mediated killing and are associated predominantly with the EBV+ sub-type in a STAT1 driven manner as discussed later in this review." (PMID 35844493, 2022). "The STAT1 staining was strong in the infiltrating cells and the tumor cells of the recurrence-free group." (PMID 35681772, 2022). "Given the observed role for STAT1 in PD-L1 expression by HNSCC cells in vitro, we next explored the impact of STAT1 on PD-1 and PD-L1 expression in the tumour microenvironment during HNSCC carcinogenesis in vivo." (PMID 35595823, 2022). "Further, the tumour inhibitory effects mediated by TRIM24 inhibition were significantly greater than STAT1 inhibition." (PMID 35595823, 2022). "Both fludarabine and ruxolitinib treatments exhibit significant impact on the tumour growth of 22Rv1 line, and diminish the protein level of STAT1, BMI1, SOX2 and NANOG in 22Rv1 tumours when compared with vehicle control." (PMID 35908276, 2022). "The inhibition of tumor growth induced by either 125I alone or in combination with EPI was compromised when STAT1-RNAi was transfected into SMMC7721 cells." (PMID 35692770, 2022). "For instance, a study found that glioma cells and other immune cells secrete IL-8, which promotes tumor migration, invasion, and mesenchymal transition by activating STAT1/hypoxia-inducible factor-1α (HIF-1α)/Snail pathway." (PMID 36193062, 2022). "By preventing angiogenesis, tumor progression, and metastasis, and inducing apoptosis, STAT1 functions as a tumor suppressor." (PMID 36497125, 2022). "In the present study, the GZMA-F2R communication promoted JAK2/STAT1 signal-induced tumor suppression both in vitro and in vivo." (PMID 35256589, 2022). "Higher EMT/tumor/CSC marker abundance was significantly associated with the carboplatin responder group including protein markers Mesothelin, Nanog, STAT1, and E-Cadherin." (PMID 35740561, 2022). "Despite the increased PD-1/PD-L1 expression observed in carcinogen induced Stat1 competent mice, tumour development was still lower than in Stat1−/− mice." (PMID 35595823, 2022). "A quantitativestudy on tumor inflammation-related mRNA expression revealed inductionsof key gene expressions, such as STAT1, CXCL10, CCL5, and CCL2, andrejuvenation of TME with enhancement in T cell, macrophage, NK cell,chemokine, and cytokine functions." (PMID 36153998, 2022). "The results of our study indicate a pro-tumour role for tumour-derived STAT1 expression in HNSCC based on its ability to enhance PD-L1-mediated immunosuppression and proliferation in both UM-SCC22A and CAL27 HNSCC cell lines." (PMID 35595823, 2022). "In this regard, some critical transcription factor genes involved in tumor immunity, such as STAT1 and STAT2, were observed to have relatively high similarities with other genes." (PMID 34980132, 2022). "STAT1 is commonly regarded as a tumor suppressor which promotes the apoptosis of cancer cells and activates immunity." (PMID 35158821, 2022). "Whilst STAT3 is thought to be significantly involved in tumor biology, STAT1 is thought to have a role in pathogen defense, growth inhibition and apoptosis." (PMID 35053592, 2022). "Inflammatory cytokines such as IL-1β, TNFα, and IFNγ are produced to combat the initial tumor via activation of NF-κB, STAT1, and NLRP3 inflammasome pathways." (PMID 36555392, 2022). "For example, STAT1 plays a critical role in mediating IFN-induced PD-L1 transcription in cancer cells, blocking T cell activation and causing tumor immune escape." (PMID 35515130, 2022). "We further demonstrate that TRIM24 potentiates the tumour promoting function of STAT1 in HNSCC cells." (PMID 35595823, 2022). "STAT1 and STAT3 were selected, as these two transcription factors are known to play prominent roles in tumorigenesis and tumor-associated immunosuppression." (PMID 35382852, 2022).
tumor (continued). "IFI35 is an interferon-stimulated gene that is involved with STAT1-mediated cellular proliferation in epithelial cells and tumor cells." (PMID 35740527, 2022). "Given that TRIM24 was selectively expressed in tumour cells of the HNSCC microenvironment potentially provides an opportunity for selectively targeting STAT1 and mitigating its tumour promoting effects in HNSCC in vivo." (PMID 35595823, 2022). "This indicates that STAT1 acts as a tumor suppressor in menopausal ER+ BC, but STAT1 actively promotes tumor growth in ER− tumors or ER+ tumors in premenopausal BC." (PMID 35401182, 2022). "In the present study, the GZMA-F2R communication at the LDPRSFLL motif of F2R suppressed tumor progression by promoting the JAK2/STAT1 signal activation-induced apoptosis." (PMID 35256589, 2022). "Previous studies have shown that STAT1 can participate in antiviral and immune defense and promote cell apoptosis and inhibit tumor growth by regulating anti-apoptotic genes such as BCL-xL, caspases, and Bax." (PMID 35692770, 2022). "In the 258 cells analyzed from this tumor tissue, PD-L1 expression correlated significantly with HIF1α expression, although PD-L1 expression correlated stronger with STAT1." (PMID 34268602, 2022). "Our observation that these populations are reduced in the bone marrow of carcinogen induced Stat1−/− mice implies that tumour-derived STAT1 plays a major role." (PMID 35595823, 2022). "We further demonstrate an important role for STAT1 in anti-tumour immunity by T cells, which supports our previous reports." (PMID 35595823, 2022). "Protein levels of p38/JAK2/STAT1 were markedly downregulated in miR-195-5p overexpressed PTC cells/tumor xenografts, whereas circRNA NRIP1 overexpression negated these impacts." (PMID 36230649, 2022). "In contrast with Stat1−/− orthotopic tumour-bearing mice, PD-1 expression was reduced in CD8+ T cells in the tumours, lymph nodes and spleens of carcinogen-induced Stat1−/− mice compared to Stat1+/+ mice." (PMID 35595823, 2022). "We determined the effects of STAT1 inhibition on tumour development and immunity in CAL27 and UMSCC22A HNSCC cell lines in vitro and in a HNSCC carcinogen-induced model in vivo." (PMID 35595823, 2022). "The tumor volume significantly decreased in the Stat1-knockdown group, compared with the control group." (PMID 34685622, 2021). "Previously, our group showed that STAT1 is essential to priming T-lymphocytes for anti-tumor immunity against aggressive HNSCC." (PMID 33668795, 2021). "STAT3 activation has been reported to show positive correlation with the proliferation and metastasis of tumor, and STAT1 enhances innate and adaptive immunity, triggering in most instances anti-proliferative and pro-apoptotic responses in tumor cells." (PMID 33748122, 2021). "STAT transcription factors are generally activated in cancer, and STAT1 phosphorylation acts as a tumor suppressor by inducing cell apoptosis and reduced cell proliferation." (PMID 34784299, 2021). "STAT1 is a well-known transcription factor that plays a critical role in tumor development, cell growth, proliferation, and apoptotic cell death." (PMID 34771447, 2021). "As a tumour suppressor, STAT1 enhances the immune response, suppresses proliferation and induces the apoptosis of tumour cells, therefore, we also measured its expression." (PMID 33546665, 2021). "STAT1 has shown tumor-suppressing properties, and when SphK1 was decreased, STAT1 signaling increased as well, leading to cell apoptosis." (PMID 33758708, 2021). "And these paracrine signals activate the STAT1 and NF-κB pathways in brain metastasis cells, which support tumor growth and chemoresistance." (PMID 34504845, 2021). "Previous studies reported an implication of STAT1 in the DNA damage response (DDR), with STAT1 activation observed upon exposure of tumor cells to genotoxic insult." (PMID 34642300, 2021).
tumor (continued). "STAT1 promotes cell apoptosis, inhibits cell growth and differentiation and plays an important role in inhibiting tumorigenesis and tumor development by regulating the interferon (IFN) system." (PMID 34838003, 2021). "While STAT1 (tumour suppressor) suppresses the aggressive invasion and cellular growth of tumour cells, STAT3 (oncogene) regulates multiple biological functions such as suppression of apoptosis, cell growth and invasion." (PMID 34631119, 2021). "Especially the STAT family members STAT1, 3, 5a, 5b, and 6 are essential for tumor progression and development of therapy resistance in advanced PCa." (PMID 34638338, 2021). "DEP screening in HCT116 cells after NUFIP1 knockdown identified 136 overexpressed and 41 underexpressed proteins, with several of those DEPs (including E2F3, STAT1) involved in regulating tumor growth." (PMID 34367967, 2021). "To explore the role of STAT1 in alisertib-mediated growth inhibition, we overexpressed STAT1 and examined the anti-tumor ability of alisertib." (PMID 34522170, 2021). "Although STAT3 and STAT5 are related to tumor immunosuppression, other members (such as STAT1) can mediate antitumor immunity, which is in contrast to the effects of STAT3 and STAT5a/b." (PMID 34943817, 2021). "In the ulcerated tumor, B cells showed increased markers associated with type-2 responses such as CCL17, IL4R, and decreases in interferon-stimulated genes (IFI44L, STAT1, IFITM1, MX1, IRF1)." (PMID 34583709, 2021). "In many cancer diseases, STAT1 overexpression also promotes tumor cell survival and immune depletion by prolonging IFN-γ signaling." (PMID 34838003, 2021). "Previously, we had determined that STAT1-/- tumor-bearing mice produced higher levels of Th17 cytokines and expressed higher IL-17 transcripts in the intestine as CAC progressed than WT mice." (PMID 34299314, 2021). "STAT1 has a dual role and is involved in the anti-tumor process, tumor progression, drug sensitivity, chemoresistance, and stemness." (PMID 33834023, 2021). "Neutrophil frequency was increased in STAT1-/- AOM/DSS animals at day 20 (early stage of tumor development), compared with WT AOM/DSS mice (p < 0.01)." (PMID 34299314, 2021). "Stat1 plays a key role in mediating responses to all interferon types, displaying anti-tumour effects on several cancers." (PMID 34858827, 2021). "Our results demonstrated that the density of p-STAT1 within tumor cells was significantly elevated in the BGS treatment group, when compared with the control group (control 31.13 ± 3.9; BGS 55.12 ± 8.4)." (PMID 34282238, 2021). "Previously, using an experimental model of CAC, we reported increased intestinal cell proliferation and faster tumor development, which were consistent with more signs of disease and damage, and reduced survival in STAT1-/- mice, compared with WT counterparts." (PMID 34299314, 2021). "In the further exploratory analysis, PTPRD/PTPRT mutation was significantly associated with increased tumor mutation burden and higher mRNA expression of JAK1 and STAT1." (PMID 34123798, 2021). "In this study, we confirmed that the positive tumor STAT1 expression implied higher MHC class I expression and PD-L1 expression on tumor cells and also peri-tumor non-tumor cells, such as TILs." (PMID 34758826, 2021). "Combination treatment with oHSV and MEKi Trametinib enhanced virus replication mediated by down-regulation of STAT1 and PKR expression or phosphorylation in BRAF V600E-mutated tumor cells as well as BRAF wt/KRAS-mutated tumor cells." (PMID 34578339, 2021). "Based on studies in mice and data from human patients, STAT1 is generally considered to function as a tumor suppressor but there is growing evidence that it can also act as a tumor promoter." (PMID 34572789, 2021). "Our research revealed that PKD3 regulates EMT and PD-L1 expression in OSCC through the ERK1/2 and STAT1/3 pathways and establishes a positive feedback loop with PD-L1 to promote tumour growth and metastasis." (PMID 33692335, 2021).
tumor (continued). "Combined inhibition targeting both the AR and JAK2/STAT1 resulted in substantial tumor suppression due to the reduction in DNA damage repair ability and increment in apoptosis." (PMID 34746227, 2021). "Our analysis revealed a significant increase in the accumulation of CD11b+ Ly6ClowLy6G+ cell populations in the spleen and blood of tumor-bearing STAT1-/- mice, compared with WT mice at the very early stages of tumor transformation." (PMID 34299314, 2021). "In the JAK-STAT1 pathway, the transcription factor STAT1 in tumor cells can regulate the expression of PD-L1 and is positively correlated with the expression of PD-L1." (PMID 34838003, 2021). "While STAT1 is required for immune surveillance, its chronic activation paradoxically potentiates and maintains tumor immune evasion by increasing the expression of immunosuppressive mediators (PD-L1, IDO1)." (PMID 33807608, 2021). "Many lines of evidence suggest that STAT1 acts as a tumor suppressor molecule in various malignancies, prompting antiproliferative and proapoptotic responses and enhancing antitumor immunity." (PMID 34299314, 2021). "While there is still controversy concerning the actual role of STAT1 in carcinogenesis, the majority of studies recognize STAT1 as a tumor suppressor." (PMID 34544433, 2021). "We detected the early production of several inflammatory cytokines in the CD4+ T cells of tumor-bearing STAT1-/- iso mice, with higher levels of IFN-γ, IL-6, and IL-17, compared with their WT counterparts." (PMID 34299314, 2021). "Accordingly, treatment with the Stat1 inhibitor fludarabine at day 14 also inhibited tumor growth and reduced Stat1 phosphorylation." (PMID 34685622, 2021). "Type I and II interferons impinge upon tumor physiology by both affecting tumor cell proliferation and activating innate and adaptive anti-tumor immune responses through STAT1 and STAT2 activation." (PMID 34830776, 2021). "As an important signal transduction factor, STAT1 was usually considered as a tumor suppressor in multiple cancers including HCC." (PMID 34178664, 2021). "In fact, both bioinformatics analyses using TCGA data and qPCR analyses using 127 paired HCC tissue samples confirmed that STAT1 was significantly upregulated in HCC tumor specimens." (PMID 33414427, 2021). "Taken together, Oct4 overexpression results in a higher tumor growth rate, which can be attenuated by Stat1 inhibition." (PMID 34685622, 2021). "The downregulation of IRF9 and VCAN expression was conserved until tumor excision, STAT1, and CDKN1A expression showed decreased tendency and STAT2, and PCNA expression were significantly reduced in the IRF9-knockdown group." (PMID 33430083, 2021). "Stat1, which is involved in anti-tumor responses following IFN-γ stimulation, was much more highly expressed in the tumors of Pik3cg−/− mice compared to WT mice." (PMID 33668795, 2021). "We demonstrated that IR elicited A549 cell apoptosis and augmented PBMCs-mediated tumor cell death through prohibiting IFNγ-mediated phosphorylation of STAT1 and STAT3 and gene expression of PD-L1 and MCL1." (PMID 34685495, 2021). "It is reported that the abnormal activation of STAT3 promotes in tumor formation, while STAT1’s abnormal activation in tumors triggers the body's anti‐tumor mechanism." (PMID 33377624, 2021). "It is suggested that STAT1 creates a radioprotective tumor microenvironment by shielding the immune responses and activating survival signaling pathways." (PMID 34638338, 2021). "There are compelling pieces of evidence that STAT1 acts as the tumor suppressor in both the tumor environment and the tumor cells themselves." (PMID 34784299, 2021). "While STAT2 expression was found to be diminished among all cultured patient samples, STAT1 overexpression was maintained in Patient 1 cell culture, and similar trends of STAT1 expression were observed for the other selected tumor lines." (PMID 34943910, 2021).